E2F7 (E2F transcription factor 7)
Diseases named in the same sentence as E2F7 in open-access papers (continued):
Sharing a sentence is not in itself a finding about the gene and the disease.
cancer (66 papers, 2009 to 2025). A tumor composed of atypical neoplastic, often pleomorphic cells that invade other tissues. "Atypical E2Fs (E2F7 and −8) can repress E2F-target gene expression independently of RB and are rarely mutated in cancer." (PMID 33922435, 2021). "Manipulating both checkpoints by combined deletion of E2F7/8 and RB would thus further enhance the risk of genomic instability and cancer than either one of these interventions alone." (PMID 33922435, 2021). "E2F7 associates with poor patient outcome in several types of cancer including PDAC and has been shown essential for mouse embryonic survival." (PMID 32660466, 2020). "The LOH method used in this study, would not by itself have excluded such an interpretation as changes close to the location of the NAV3 gene (for example, the cancer implicated gene E2F7) would also have shown loss of heterogeneity in this assay." (PMID 22173670, 2012). "In cancer biology, E2F7 is associated with poor survival in squamous cancers." (PMID 31703415, 2019). "Since the relative chemoresistance of these carcinomas appears to be linked to high E2F7/E2F1 ratio, targeting CtBPs may enhance the expression of E2F1 and the apoptotic response." (PMID 24955216, 2014). "This study performed in vitro experiments to demonstrate that reducing E2F7 levels has anti-cancer effects on LUAD, achieved by hindering cell growth through the AKT/mTOR signaling pathway and increasing apoptosis signals." (PMID 38760774, 2024). "Despite its general classification as a cell cycle repressor, E2F7 exhibits upregulation and oncogenic activity in diverse cancer types." (PMID 39590378, 2024). "To delineate the transcriptional control of this module, we investigated associated TFs, highlighting the roles of prominent cancer‐associated TFs, such as CENPA, HNF1A, and E2F7." (PMID 39102671, 2024). "The balance between the expression of E2F7 and other E2F factors is well described also in differentiation processes during both development and cancer progression and aggressiveness." (PMID 36765037, 2023). "E2F7 is also known to modulate DNA repair and promote cell proliferation and differentiation in a variety of cancer types." (PMID 36879901, 2023). "Confined to the definition of E2F1 antagonist, the role of E2F7 in cell cycle regulation has been limited for long time to its canonical function as transcriptional repressor and onco-suppressor in some cancer settings." (PMID 36765037, 2023). "Recent studies have reported that E2F7 is upregulated significantly and promotes tumorigenesis in various cancer types." (PMID 37028765, 2023). "Whereas, as a specifical atypical member of this family, E2F7 was described as a repressor against its downstream genes and exerted oscillatory and controversial functions in cancers." (PMID 35924788, 2022). "One novel potential regulatory mechanism of p63 involves E2F family members, notably E2F1 and E2F7, which regulate cell cycle gene expression in HPV infection and HPV-associated cancers." (PMID 35712470, 2022). "Whereas, the effects of E2F7 on human cancers are controversial because of its ambiguous functions ever reported." (PMID 35924788, 2022). "Some cancer drivers displayed both decreased accessibility and decreased mRNA levels, e.g., Brca1, E2f7 and Myh11, while others displayed increased accessibility and associated mRNA upregulation, e.g., Msi2, Bace2." (PMID 35269430, 2022). "As a transcription factor, E2F7 can bind the promoters of target genes and regulate cancer progression." (PMID 35201478, 2021). "E2F1, E2F2 and E2F7 proteins, which were upregulated in most of the cancer types and appear as high centrality nodes in the bipartite graphs, regulate around 224, 93 and 74 high centrality genes, respectively." (PMID 34728699, 2021). "As an atypical E2F transcription factor, E2F7 functions as a key regulator of cell cycle progression, and its inactivation leads to spontaneous cancer formation." (PMID 35201478, 2021).
cancer (continued). "Recently, E2F7 has been reported to be closely related to drug resistance, cell cycle, and DNA damage repair in several cancers." (PMID 34226533, 2021). "According to the previous studyy, multiple binding site of E2F7 has been identified in other cancer types." (PMID 32064771, 2020). "This global approach further highlighted strong correlations between A3B and expression of E2F1, E2F2, E2F7, and E2F8 and indicated that the association between A3B, this signal transduction pathway, and the cell cycle is evident in many cancer types." (PMID 30723127, 2019). "circPRKCI adsorbed miR-545 and miR-589 by “sponge action” and relieveed its target inhibition, leading to up-regulation of the cancer-promoting transcription factor E2F7." (PMID 31857500, 2019). "In this study, we successfully identified CDKN1β and E2F7 as cellular cell cycle targets of miR-181a, and have also shown its effects on important pathways in cancer progression." (PMID 25901570, 2015). "The expression profiles of Hmox1, Pten and E2f7 genes were similarly altered by mastic oil in the majority of test cancer cell lines." (PMID 20003503, 2009). "Besides, studies have ascertained that E2F7 can be modulated by miRNA, affecting cancer progression." (PMID 38073330, 2024). "In addition, in two human cancer cell lines (U2O and HeLa), E2F7 recruited the corepressor C-terminal binding protein to repress the transcription of E2F1 in a C-terminal binding protein-dependent manner, leading to reduced cell proliferation." (PMID 39613162, 2024). "The prognostic risk model based on six DMGs in our study, namely FAM83A, S100A16, E2F7, ANLN, C1QTNF6 and GAPDH, suggests that they might reveal causes of the cancer development and tumorigenesis in LUAD." (PMID 38711158, 2024). "E2F7 is a cellular context-dependent transcription factor that might act as a positive or negative regulator in different cancer types." (PMID 37028765, 2023). "Our data are in line with this “non canonical” function of E2F7 in supporting cancer progression." (PMID 36765037, 2023). "The frequent deregulation of E2F7 in human cancers has been established." (PMID 35201478, 2021). "E2F7 abnormalities seem to have a crucial function in the growth of cancer cells." (PMID 34781924, 2021). "Two primary miR-545 targets are RIG-1 and E2F7 in cancer cells." (PMID 31409777, 2019). "Similarly, with forced expression of E2F7, miRNA-302a/d was incapable of suppressing the cancer cell growth." (PMID 30326936, 2018). "Therefore, disrupting the balance between them, by either transcriptional dysregulation or increased cytoplasmic distribution of E2F7, may lead to cancer development." (PMID 39613162, 2024). "Therefore, the opposite function of E2F7 in different cancers relies on individual cancer types." (PMID 35201478, 2021). "However, the difference is that heterologous overexpression of LINC00174 also accelerated the migration and invasion ability of CRC cells, and may promote EMT protein and E2F7 by competitively binding miR-3127-5p to play a cancer-promoting role in CRC." (PMID 34226413, 2021). "Cancers displaying unfavorable risk with high ALT (BRCA, SARC, and LUAD) may be regulated by the transcriptional factors E2F4, TFDP1, E2F1, E2F7, and SIN3A (FDR = 0.001) in the DNA repair pathway, including genes repairing DNA damage such as CENPI, CLSPN, TOPBP1, and MCM4." (PMID 32784588, 2020). "In addition, E2F7 has also been shown to be activated by Akt signaling in carcinomas." (PMID 32660466, 2020).
cancer (continued). "Studies showed that E2F7 could promote cancer cell proliferation, migration, and metastasis." (PMID 31183379, 2019). "Recent studies have implied that downregulation of E2F7 could induce cancer cell apoptosis." (PMID 31409777, 2019). "For cell cycle regulation and cancer, the genes CCND1 and E2F7 (cell cycle regulation) and BRCA2, NF2, BRCA1, and NF1 (cancer) were found to be upregulated relative to humans." (PMID 40149424, 2025). "In our study, we found that E2F7 was significantly up-regulated in CRC cells, fostered the malignant progression of cancer cells, and hampered the killing effect of NK cells on CRC cells by activating RAD18 transcription." (PMID 38073330, 2024). "Proliferative cancer cells specifically express TFs involved in cell proliferation, including E2F TF family members (E2F2, E2F8, and E2F7)." (PMID 37853464, 2023). "Then, we predicted and validated potential transcription factors (including E2F7, KLF5 and FOXM1) and therapeutic drugs (such as cyclophosphamide, vinblastine, and gefitinib) that target ferroptosis regulators in cancer." (PMID 34975326, 2022). "The results showed that the mRNA levels of E2F1, E2F2, E2F3, E2F5, E2F7 and E2F8 were significantly lower in adjacent tissues compared with those in carcinoma tissues." (PMID 32117628, 2020). "In accordance with the mRNA expression levels obtained from GEPIA, the protein expression of E2F1, E2F2, E2F3, E2F5, E2F7 and E2F8 were significantly higher in carcinoma tissues." (PMID 32117628, 2020). "Next, we validated the expression levels of miRNA-302a/d and E2F7 in HCC tissue samples using qRT-PCR in 154 HCC biopsies, 34 of which were pairs of tissue from para-carcinoma tissues." (PMID 30326936, 2018). "Similarly, by exploring Cancer Cell Line Encyclopedia (CCLE) database, we also found a general upregulation of E2F7 in most of the HCC cell lines." (PMID 35924788, 2022). "In addition, since miR-424-5p regulates the proliferation and apoptosis of cancer cells in HCC, and it can also be used as a potential biomarker in the diagnosis of liver cancer, the relationship among MYLK-AS1, miR-424-5p, E2F7 and VEGFR-2 signaling pathway in HCC cells was studied." (PMID 33168027, 2020). "The roles of DCBLD2, E2F7, and KRT6A have not been explored in PDAC but these proteins are known to have context dependent effects in various cancers." (PMID 30092011, 2018).
adenocarcinoma (2 papers, 2022 to 2023). A common cancer characterized by the presence of malignant glandular cells. "Kaplan-Miere survival analysis of all adenocarcinoma patients showed that high expression of E2F7 was associated with shorter OS (P = .002)." (PMID 35984189, 2022).
infection (2 papers, 2023 to 2025). The state of being infected such as from the introduction of a foreign agent such as serum, vaccine, antigenic substance or organism. "Therefore, one could speculate that during SARS-CoV-2 infection, the virus may interfere with the E2Fs genetic programming towards an inhibition of cell death and promotion of cellular proliferation through E2F7 to ensure viral replication and productive infection." (PMID 36879901, 2023).
vasculopathy (1 paper, 2020). "Thus, our identified DEGs (RRM2, APC, CHEK1, E2F6, TYMS, E2F7, and CDK6) from the cluster 2 subnetwork are highly related to and consistent with the members of the signaling pathways associated with the immune system, apoptosis, the cell cycle, and vasculopathy." (PMID 32426333, 2020).
E2F7 also shares sentences with these, for which no sentence is quoted: papillary thyroid cancer (3 papers); rectal adenocarcinoma (3); chronic myeloid leukaemia (2); lymph node metastasis (2); malignant glioma (2); Alzheimer disease (1); anaplastic oligodendroglioma (1); anaplastic thyroid cancer (1); bladder urothelial carcinoma (1); cervical squamous cell carcinoma (1); cholangiocarcinoma (1); colon adenocarcinoma (1); esophageal squamous cell carcinoma (1); head and neck cancer (1); infertile (1); large-cell lung carcinoma (1); multiple myeloma (1); Nephroblastoma (1); oligodendroglioma (1); opioid dependence (1); oral cancer (1); renal carcinoma (1); thyroid tumor (1).